RUNX2 (RUNX family transcription factor 2)
Diseases named in the same sentence as RUNX2 in open-access papers (continued):
Sharing a sentence is not in itself a finding about the gene and the disease.
breast carcinoma (continued). "In vitro experiments using ER+ MCF7 breast cancer cells demonstrated a role of RUNX2 in inducing EMT and metastasis through its target gene SNAI2 via the Wnt/TGFβ pathways." (PMID 36831308, 2023). "While displaying context-dependent roles in breast cancer, RUNX2 has built up a prominent reputation as a driver of breast cancer metastasis." (PMID 36831308, 2023). "When RUNX2-orchestracted breast cancer growth was studied, RUNX2 silencing in a breast cancer cell line inhibited cancer proliferation in a plate cloning assay and in a subcutaneous neoplasia model of BALB/c nude mice." (PMID 37108164, 2023). "In breast cancer, RUNX2 expression correlates with the triple negative subtype through cross-talk with estrogen receptor signaling." (PMID 37256183, 2023). "In metastatic breast cancer cells, phosphorylation of RUNX2 by AKT to enhance RUNX2 mediated transcription has been shown to increase expression of genes involved in tumor cell invasion." (PMID 36831308, 2023). "In support of this, RUNX2 expression was positively correlated with an aggressive phenotype of human breast cancers through immunohistochemical analysis of primary tumors." (PMID 36831308, 2023). "The expression of Runx2 is disrupted in breast cancer and induces the expression of EMT-related transcription factors and metastasis-related genes." (PMID 37968694, 2023). "Subsequently, RUNX2 was found to promote progression and bone metastasis in prostate and breast cancers." (PMID 37519798, 2023). "In this study, we found that restoration of miR-218 using miR-218 containing exosomes downregulates Runx2 in breast cancer cells at the mRNA levels." (PMID 37968694, 2023). "Our results indicate that RUNX2 is a promising potential target for the future treatment strategies of breast cancer." (PMID 35534547, 2022). "RUNX2 regulates EMT in breast cancer through the activation of the Wnt pathway, and in prostate cancer, hyperactivation of AKT by RUNX2 has been observed." (PMID 35805994, 2022). "Together, our study demonstrated that the RUNX2, NuRD(MTA1), and CRL4B complexes are physically associated and functionally linked to the promotion of EMT and bone metastasis of breast cancer cells." (PMID 35534547, 2022). "These analyses indicated that only RUNX2 expression was significantly increased in breast cancer compared to normal samples." (PMID 35534547, 2022). "For the purpose, we conducted multifaceted analyses both in vitro and in vivo to verify the dysfunction and the concomitant mechanism of RUNX2 in modulating proliferation, migration, invasion, and chemoresistance of breast cancer cells." (PMID 36483054, 2022). "Increased carboxypeptidase-D expression was associated with the upregulation of progression markers VEGF-C and Runx2 during breast cancer progression." (PMID 35686102, 2022). "In summary, our results showed that RUNX2 expression was upregulated in multiple carcinomas including breast cancer, while PPARα was downregulated in breast cancer, suggesting the potential of RUNX2 as a biomarker of breast cancer." (PMID 35534547, 2022). "In thyroid and breast cancers, RUNX2 transcription requires three distantly located enhancers (ENHs) in a chromatin three-dimensional looping." (PMID 36429115, 2022). "In this study, we set out to better understand the changes induced by Runx2 in bone-derived breast cancer cells." (PMID 35884497, 2022). "In this study, we examined the role of Runx2 in tubulin acetylation and its impact on MTs’ stability, and the sensitivity of bone-derived breast cancer cells to microtubule-targeting agents." (PMID 35884497, 2022). "RUNX2 is closely related to the proliferation, invasion, and bone metastasis in multiple cancer types, such as osteosarcoma, breast cancer (BC), prostate cancer, gastric cancer, colorectal cancer, and lung cancer." (PMID 36510562, 2022). "Depletion of RUNX2 had a stronger inhibitory effect on the proliferation of breast cancer cells than the suppression of RUNX1 or RUNX3." (PMID 35534547, 2022).
breast carcinoma (continued). "Simultaneously, the expression of MMP1 was significantly upregulated in SUM-149 breast cancer cells with RUNX2 overexpression." (PMID 36483054, 2022). "Ten breast cancer samples were collected and performed tissue microarray analysis via immunohistochemical staining to examine the expression of RUNX2 and PPARα." (PMID 35534547, 2022). "In this study, we investigated the potential role of RUNX2 in the development of breast cancer and bone metastasis." (PMID 35534547, 2022). "recently indicated the aberrant phosphorylation and expression of RUNX2 in breast cancer invasion and gastric cancer metastasis, respectively." (PMID 36483054, 2022). "Runx2 promotes bone metastasis of breast cancer through the ITGBL1-mediated TGF-β signaling pathway." (PMID 35342401, 2022). "Further, the expression of RUNX2 was associated with the infiltration of CD4 +T cells, neutrophils, B cells, CD8 + T cells, macrophages, and dendritic cells in breast cancer." (PMID 36092942, 2022). "Accordingly, decreased OPN and Runx2 expression following CBFB-knockdown suggests a potential role for CBFB in the treatment of bone metastasis in patients with breast cancer." (PMID 35903297, 2022). "The inhibition of DLX6-AS1 in MCF-7 breast cancer cells enhances the cell apoptosis process by directly sponging miR-505-3p to upregulate runt-related transcription factor 2 (RUNX2)." (PMID 36613528, 2022). "Our study suggests that RUNX2 is a promising potential target for the future treatment strategies of breast cancer." (PMID 35534547, 2022). "PPARα and SOD2, which inhibited breast cancer bone metastasis, were found to be the target genes of the RUNX2/NuRD(MTA1)/CRL4B complex." (PMID 35534547, 2022). "In breast cancer, RUNX2 has been found to promote breast cancer progression by driving EMT-like change and DNA damage." (PMID 35534547, 2022). "As a member of RUNX family, RUNX2 is a critical regulator and master organizer in bone development and several malignances, including lung cancer, breast cancer, pancreatic cancer, liver, prostate cancer, ovarian cancer, etc.." (PMID 35267576, 2022). "Consistent with our observation that PPARα was a downstream target of RUNX2, the expression of PPARα was found to be downregulated in these breast cancer samples and the level of its expression is negatively correlated with RUNX2." (PMID 35534547, 2022). "The miR-135 and miR-203 were found to inhibit the malignant phenotypes of breast cancer cells by repressing RUNX2." (PMID 36429115, 2022). "Breast cancer cells with higher RUNX2 expression have a stronger ability to migrate, partly due to the upregulation of EMT-related genes such as MMP2, MMP9, MMP13, BSP, etc.." (PMID 36429115, 2022). "Runx2 is highly expressed in breast cancer cell lines and breast primary tissues that are more prone to bone metastasis." (PMID 35342401, 2022). "Current studies have confirmed that RUNX2 is closely related to the proliferation, invasion, and bone metastasis of multiple cancer types, such as osteosarcoma, breast cancer (BC), prostate cancer, gastric cancer, colorectal cancer, and lung cancer." (PMID 36510562, 2022). "The increased expression of RUNX2 in breast cancer cells that metastasize to the bone indicates protumorigenic and pro-metastatic roles, although the detailed molecular mechanism is not very clear." (PMID 35534547, 2022). "As a downstream molecule of the PI3K/AKT and MAPK pathway, RUNX2 can regulate metastatic properties of human prostate cancer and breast cancer cells." (PMID 34606473, 2021). "Aberrant expression of Runx2 in the metastatic MDA-MB-231 breast cancer cell line has been shown to promote an invasive and migratory phenotype." (PMID 34503118, 2021). "Lastly, we found that ABL expression in highly metastatic breast cancer MDA-MB231 cells is associated with their invasive capacity and that ABL-mediated invasion is abolished by depletion of endogenous RUNX2 or MMP13." (PMID 34136397, 2021).
breast carcinoma (continued). "BML284-treated macrophage-derived CM also downregulated Lrp5, Runx2, and TGFβ, and it reduced the size of human breast-cancer-tissue fragments (ER-/PR+/HER2+) ex vivo in 3 days." (PMID 34830748, 2021). "We found that RUNX2 expression significantly varied in different stages, subclasses, and histological subtypes of breast cancer." (PMID 34485309, 2021). "Lastly, we show that ABL expression in highly metastatic breast cancer MDA-MB231 cells is associated with their invasive capacity and that ABL-mediated invasion is abolished by depletion of endogenous RUNX2 or MMP13." (PMID 34136397, 2021). "miR-302b maintain SOX2 and c-MYC to produce cytokine-induced cancer stem cell-like properties in breast cancer cell co-cultured with immature adipocyte; whilst miR-302b in breast cancer targets RUNX2, an activator of PI3K/AKT signaling." (PMID 33482868, 2021). "Recently, it was shown that silencing of Runx2 in MDA-231 breast cancer cells results in delayed metastasis and late stage tumor development." (PMID 34503118, 2021). "The IGF-1Rβ/AKT axis was shown to get activated in bone-seeking breast cancer cells after the knockdown of the transcription factor of osteogenic differentiation, namely runt-related transcription factor 2 (RUNX2)." (PMID 34064589, 2021). "Tan and colleagues suggest that the aberrant Runx2 expression and osteomimetic behavior observed in bone metastatic breast cancer is a consequence of epithelial to mesenchymal transition (EMT)." (PMID 34503118, 2021). "The copy number change of the RUNX2 gene was only positively correlated with the infiltration of four types of immune cells in breast cancer: CD8+T cells, CD4+T cells, macrophages, and neutrophils." (PMID 34485309, 2021). "We recently reported a similar example of reliance among different elements in the regulation of RUNX2 expression in thyroid and breast cancer." (PMID 34680347, 2021). "In breast cancer, it was found that RUNX2 functioned through the androgen receptor to regulate prolactin-induced protein (PIP), a new biomarker for keratoconus." (PMID 34233613, 2021). "Among these genes, Runt-related transcription factor 2 (RUNX2) is a key regulator of bone-related gene expression in breast cancer cell lines." (PMID 33203195, 2020). "The overexpression of RUNX2 and its role in tumor progression in breast cancer have been demonstrated in different studies." (PMID 33375067, 2020). "This phenomenon was first described in prostate and breast cancers, preferentially metastasize to bone, where RUNX2 is a master regulator during the transformation of cancer cells into osteomimetic cells." (PMID 33287223, 2020). "Accumulating evidence indicates the involvement of several transcription factors, Runx-2 and Bach1, in breast cancer metastasis to bone." (PMID 33081224, 2020). "Very recently, it was confirmed that miR-302b has a tumor suppressor function in breast cancer, and its reintroduction reduces tumor progression by targeting Runt-related transcription factor 2 (RUNX2)." (PMID 32806777, 2020). "In summary, we explored the mechanism of SET7/9-mediated breast cancer cell proliferation, migration, and invasion through the activation of RUNX2." (PMID 32102992, 2020). "Like many other transcription factors, the upregulation of RUNX2 is regarded as an important contributor in breast cancer; however, the exact mechanism of RUNX2 is only beginning to be elucidated." (PMID 32102992, 2020). "Endothelin-1 can activate Runx2 and confer an osteomimetic phenotype in breast cancer cells, contributing to colonization and osteolysis." (PMID 33123472, 2020). "CD44-ICD has been shown to regulate the expression of numerous genes via its interaction with RUNX2 in breast cancer cells." (PMID 33062960, 2020). "Recent reports have identified the interaction of RUNX2 with CD44-ICD on the promoter of the MMP-9 gene in breast cancer." (PMID 33062960, 2020).
breast carcinoma (continued). "Next, we monitored the proliferation capacity of breast cancer cells following the depletion of SET7/9 together with the overexpression of RUNX2." (PMID 32102992, 2020). "In detail, we demonstrated a significant association between [99mTc]Tc-Sestamibi uptake and both the number of RANKL- and RUNX2-positive breast cancer cells (BOLCs)." (PMID 32164267, 2020). "In this study, we mainly focus on the target of RUNX2 by SET7/9 contributes to breast cancer progression." (PMID 32102992, 2020). "RUNX2 is closely related to the occurrence and development of various tumours, such as leukaemia and breast cancer." (PMID 32943991, 2020). "Overexpression of OPN and RUNX2 was found to be negatively correlated with the OS of patients with breast cancer." (PMID 32934344, 2020). "In our study, we reveal a new model to illuminate the contribution of the activation of RUNX2 expression by SET7/9 in breast cancer to carcinogenicity." (PMID 32102992, 2020). "In breast cancer, the expression of RUNX2 has been related to both BOLCs and cancer metastatization." (PMID 32498363, 2020). "RUNX2 overexpression has been reported in breast cancer, pancreatic cancer, prostate cancer, lung cancer, ovarian epithelial cancer and melanoma." (PMID 32204402, 2020). "In the current study, we show that CADD522 inhibits mitochondrial oxidative phosphorylation by decreasing the mitochondrial oxygen consumption rate (OCR) and ATP production in human breast cancer cells in a RUNX2-independent manner." (PMID 33196708, 2020). "RUNX-2 can promote breast cancer bone metastasis by increasing integrin α5-mediated colonization or inducing RANKL-mediated osteoclast activation." (PMID 33081224, 2020). "Runx2 and PTHrP are usually highly expressive in metastatic breast cancer cells and act as promoters in tumor-induced osteoclastogenesis 40,51." (PMID 32226538, 2020). "RUNX2, the master transcription factor for osteogenic differentiation, is overexpressed in several tumor tissues, including pancreatic cancer, breast cancer, ovarian epithelial cancer, prostate cancer, lung cancer, thyroid cancer and in osteosarcoma." (PMID 32168858, 2020). "CD44-ICD has been shown to interact with the master regulator of osteoblastogenesis, RUNX2, in the nucleus of breast cancer cells." (PMID 33062960, 2020). "Targeting RUNX2 represses cell growth and metastasis in lung cancer cells and inhibits the progression of breast cancer to metastatic bone disease." (PMID 33365318, 2020). "Then, human bone samples from the femoral heads of patients undergoing total hip replacement or proximal femur replacement with breast cancer metastases to the bone were stained for RUNX2, OCN, IL-6, and alpha-SMA using multi-plex immunofluorescence." (PMID 30813947, 2019). "By targeting RUNX2 (runt-related transcription factor 2), miR-203 and miR-135 impair the progression of breast cancer." (PMID 31073374, 2019). "Studies have indicated that Runx2 plays important roles in tumor cell growth and migration, as wells as in bone metastasis of breast cancer." (PMID 31781337, 2019). "Human bone metastatic breast cancer patient samples exhibited isolated areas of cells that were positive for both RUNX2 and osteocalcin expression demonstrating the presence of osteoblasts among tumor cells." (PMID 30813947, 2019). "Studies by others have identified CD44 cleavage product (CD44-ICD) in complex with RUNX2 on the promoter of the MMP-9 gene in breast cancer cells." (PMID 31331331, 2019). "Human patient samples of bone metastatic breast cancer were stained using immunofluorescence for RUNX2 (green, 488) and osteocalcin (OCN, red, 594)." (PMID 30813947, 2019). "Runx2 is expressed in ER+ human breast cancer cell lines and participates in mammary gland development." (PMID 31781337, 2019). "CD44-ICD was shown to regulate the expression of several genes through its interaction with RUNX2 in breast cancer cells." (PMID 31331331, 2019).
breast carcinoma (continued). "Recent studies also discovered Runx2 functioned an important role in promoting breast cancer metastasis." (PMID 30930692, 2019). "In human tissue from patients with bone metastatic breast cancer, we found areas of RUNX2-positive, osteocalcin-positive expressing osteoblasts in the tumor microenvironment." (PMID 30813947, 2019). "qRT-PCR analysis confirms that thyroid and breast cancer cells express the highest RUNX2 levels among the testes cell lines." (PMID 31395086, 2019). "Osteotropic breast cancers overexpress bone mineralization and differentiation proteins such as Runt-related transcription factor 2 (RUNX2), bone sialoprotein II, osteoactivin, ectoenzyme ectonucleotide pyrophosphatase 1 (ENPP1) and adrenomedullin (AM)." (PMID 29805773, 2018). "It has been demonstrated that RUNX2 is able to control the metabolic pathways involved in breast cancer progression by repressing SIRT6 tumor suppressor." (PMID 30463392, 2018). "Though, BITC inhibits breast cancer, lesser expression of NF-κB and runt-related transcription factor 2 (RUNX2) induce osteolytic bone resorption." (PMID 30445746, 2018). "Runx2 promotes tumor growth in bone and knocking down Runx2 in cancer cells protects from breast cancer-induced osteolytic disease, positioning Runx2 as an attractive target to reduce bone metastatic burden." (PMID 29780354, 2018). "A specific feature of bone metastatic breast cancer cells is that they exhibit pathologically elevated expression of bone-related genes [e.g., Runt-related transcription factor 2 (Runx2)] and signaling pathways, including the Wnt pathway." (PMID 29780354, 2018). "Runx2 is required for mammary gland development, and Runx2 deletion increased animal survival in a mouse model of breast cancer with reduced proliferation and cyclin D expression." (PMID 30202094, 2018). "The extensive expression studies demonstrated that the expression level of RUNX2 is aberrantly elevated in numerous cancer tissues as compared to their corresponding normal ones including pancreatic cancer, breast cancer, prostate cancer and osteosarcoma." (PMID 29558908, 2018). "Down-regulation of ANCR increases RUNX2 expression and promotes breast cancer cells invasion and metastasis in vitro and in vivo." (PMID 28978036, 2017). "In vitro mammosphere formation assays support a role for phospho-Ser294-PRs via growth factor (EGF) signaling as well as RUNX2 as potent drivers of breast cancer stem cell fate." (PMID 28412963, 2017). "RUNX2 is known to be frequently up-regulated in breast cancer patients, and higher RUNX2 level often leads to the poor prognosis of patients." (PMID 28978036, 2017). "Taken together, these data suggests that ANCR is able to inhibit RUNX2 expression, which plays a pivotal role in repression of breast cancer metastasis in vivo." (PMID 28978036, 2017). "In vitro mammosphere formation assays confirmed that phosphorylated PRs and RUNX2 are potent drivers of breast cancer stem cell expansion." (PMID 28412963, 2017). "Downstream, ANCR inhibits breast cancer cell migration and breast cancer metastasis by decreasing RUNX2 expression in vitro and in vivo." (PMID 28978036, 2017). "We then assessed the expression of ANCR and RUNX2 in a panel of paired tumor and normal primary tissue specimens collected from breast cancer patients (N=25)." (PMID 28978036, 2017). "The RUNX2 transcription factor promotes breast cancer growth and metastasis through interactions with a variety of cofactors that activate or repress target genes." (PMID 29050333, 2017). "The RUNX2 gene has been previously reported to be a novel regulator of mammary epithelial cell fate in development and breast cancer, and it has also been shown that exogenous transgenic expression of RUNX2 in mammary epithelial cells blocked milk production." (PMID 28558656, 2017). "More interestingly, we found that the ANCR expression was negatively correlated with RUNX2 in breast cancer cell lines." (PMID 28978036, 2017).